CXCR4 (C-X-C motif chemokine receptor 4)
Diseases named in the same sentence as CXCR4 in open-access papers (continued):
Sharing a sentence is not in itself a finding about the gene and the disease.
gastric cancer (continued). "Elevated expression of CXCR4 and/or CXCL12 expression has been examined in larger tumors and lymphatic invasion samples in gastric cancer, as well as decreased response to radio- and chemo-therapy in various cancer types." (PMID 38748299, 2024). "As for CXCR4 and GLIPR1, they were up-regulated in our results and in STAD patients, indicating their oncogenic effect on gastric cancer." (PMID 38368374, 2024). "CXCR4 showed an up-regulated trend and NFE2L2 showed a down-regulated trend in stage I and stage II gastric cancer samples." (PMID 38221932, 2024). "Previous studies have highlighted COL1A1, YAP1 and chemokine receptor CXCR4 as targets of RUNX2 that facilitate the in vitro invasion and metastatic potential of gastric cancer cells." (PMID 37256183, 2023). "In this section, we first treated gastric cancer cells with SDF-1α overexpressed lentivirus and Curcumol, and then Curcumol's regulatory effect on SDF-1α/CXCR4 axis was verified." (PMID 36131788, 2022). "We have demonstrated that curcumol can simultaneously reduce the expression of NF-κB, SDF-1α and CXCR4 in CAG animal models and gastric cancer in vivo and in vitro experiments." (PMID 36159583, 2022). "In gastric cancer, high-expressed CXCL12 and CXCR4 have been found to promote the migration, invasion and EMT of gastric cancer cells, and are closely related to the poor prognosis." (PMID 35264069, 2022). "It has been found that the CXCR4/SDF-1 axis promotes the development of many cancers, including colorectal, hepatocellular, and gastric cancers." (PMID 36564369, 2022). "This study showed that Curcumol represses the VEGF, SDF-1α, and CXCR4 expressions in both CAG model and gastric cancer cells, and it also suppresses the activity, migration, and invasion of gastric cancer cells, inducing the apoptosis of gastric cancer cells." (PMID 36131788, 2022). "The experimental results show that CXCR4 expression was higher in gastric cancer cells, while TAB1 expression was higher in normal gastric tissues than in gastric cancer tissues." (PMID 35509844, 2022). "We subsequently added SDF-1α overexpressing lentivirus to the Curcumol-treated group and found that the expressions of SDF-1α, CXCR4, and VEGF protein increased, and the inhibitory effect of Curcumol on gastric cancer cells was withdrawn." (PMID 36131788, 2022). "Afterwards, our results indicated that high levels of SDF-1α elevated SDF-1α, CXCR4, and VEGF protein levels in gastric cancer cells." (PMID 36131788, 2022). "In-depth detection on SDF-1α, CXCR4, and VEGF protein expressions showed that the SDF-1α, CXCR4, and VEGF protein levels in gastric cancer cells were greatly retarded after the treatment with Curcumol and positive drug Fuzheng Huowei decoction." (PMID 36131788, 2022). "Other studies demonstrated the positive effect of the chemokine SDF-1 in the process of the proliferation of gastric cancer cell line NUGC4, characterized by the high expression of CXCR4." (PMID 35328253, 2022). "We demonstrated that Curcumol would simultaneously reduce VEGF, SDF-1α, and CXCR4 protein levels in the CAG animal model, and the relevant outcomes from in vivo and in vitro experiments of gastric cancer were alike." (PMID 36131788, 2022). "In this study, the CAG model, in vitro cultured gastric cancer cells, and participating nude mice were treated with Curcumol, and alterations in SDF-1α/CXCR4/VEGF expression were estimated using the assays of immunohistochemistry and Western blot." (PMID 36131788, 2022). "The present study was designed to investigate the expression of VEGF, CXCR4 genes, and CD34 (for the assessment of MVD) in gastric cancer tissue using real-time PCR and immunohistochemistry." (PMID 35877436, 2022). "It was been shown that this crosstalk between CXCR4 and CXCR2 contributed to EMT, migration and invasion of gastric cancer." (PMID 34012923, 2021).
gastric cancer (continued). "Previous study has confirmed that the positive crosstalk between CXCR4 and EGFR increases the migration ability in gastric cancer." (PMID 34555268, 2021). "For example, expression levels of CXCR3, CXCR4, and CXCR5 displayed a marked increase in gastric cancer and were significantly correlated to the prognosis of patients." (PMID 34337085, 2021). "Previous studies have demonstrated that CXCR4 can contribute to EMT, migration, and invasion in gastric cancer through immune and inflammatory pathways." (PMID 34247148, 2021). "CD44-mediated gastric cancer cell invasion and metastasis by binding to human epidermal growth factor receptor 2 (HER2) inhibits miR-139 and upregulates the miR-139 target gene, C-X-C chemokine receptor type 4 (CXCR4)." (PMID 34944493, 2021). "Cancer-associated fibroblasts (CAFs) are apparently responsible for the invasion process and metastatic actions in some cancers, among them gastric cancer is titled, through the activation of CXCL12/CXCR4 signalling." (PMID 29867026, 2018). "Amphiregulin AREG and HB-EGF were provoking factors of intensified proliferation, migration, and functional CXCR4 expression in gastric cancer NUGC4 cells, with the overexpression of CXCR4." (PMID 29867026, 2018). "Real-time PCR and Western blotting were used to examine the mRNA and protein levels of CXCR4 and CXCR7 in five gastric cancer cell lines (HGC-27, MGC-803, BGC-823, SGC-7901, and MKN-28)." (PMID 27716367, 2016). "First, we examined CXCR4 expression in gastric cancer cell line, AGS, by using RT-PCR and found that CXCR4 transcripts are highly expressed in this cell line." (PMID 24659999, 2014). "In the studies on gastric cancer a direct relationship between PGK1 signalling and CXCR4 is observed and supports the importance of interaction between glucose metabolism and chemokine function." (PMID 24376734, 2013). "Thus, CXCR4 may be a potential down-stream effector of RhoE in gastric cancer metastasis." (PMID 24312338, 2013). "Suppression of CXCR4 expression by plumbagin was found to correlate with the inhibition of CXCL12-induced migration and invasion of both breast and gastric cancer cells." (PMID 21880153, 2011). "There was another obvious upregulation of CXCR4 expression in cancer cells after they were co-cultured with macrophage, an alternative source of TNF-α in gastric cancer microenvironment." (PMID 20699000, 2010). "A subsequently Spearman's rank correlation test showed there was a positive correlation between the level of CXCR4 mRNA and that of TNF-α in 34 primary gastric cancers." (PMID 20699000, 2010). "In gastric cancer KATO III cells, tatridin A reduces invasiveness by antagonizing PGK1, an oncoprotein that promotes proliferative and anti-apoptotic signaling cascades, along with the downregulation of chemokine receptor 4 (CXCR4) and β-catenin." (PMID 41149747, 2025). "Regarding the differential effect of PCDHGA9 on the Wnt/β-catenin pathway between CRC and gastric cancers, varying HOXA1 and CXCR4 expression levels in these cancers might explain this difference." (PMID 39587482, 2024). "Additionally, DARPP-32 significantly impacts CXCR4 and CXCL-12 expression, critical for invasive behavior in gastric cancer." (PMID 39767693, 2024). "The database analysis and western blot analyses show CXCR4 is not expressed in gastric cancer cells, including MGC803 and Hs746T." (PMID 37950281, 2023). "The clinical significance of CXCR4 expression in gastric cancer has not been clarified and is still controversial." (PMID 35877436, 2022). "On the basis of previous research, this study was committed to exploring curcumol's therapeutic effect on CAG and gastric cancer, to explore its possible mechanism of action from the perspective of anti-inflammatory, taking the SDF-1/CXCR4 axis as an entry point to clarify the target of its role." (PMID 36159583, 2022).
gastric cancer (continued). "Moreover, CXCL12 can induce epithelial-mesenchymal transition (EMT) and gastric cancer metastasis possibly through the interaction between MET proto-oncogene (c-MET) and CXCR4." (PMID 35265130, 2022). "Furthermore, the overexpression of SDF-1α brought about an upregulation in SDF-1α, CXCR4, and VEGF protein levels, and Curcumol's inhibitory effect on gastric cancer cells was withdrawn." (PMID 36131788, 2022). "In addition, it has been reported that peritoneal metastasis in gastric cancer proves to be related to the interaction between VEGF, CXCR4, and CXCL12." (PMID 36131788, 2022). "The results demonstrated that the pathway could regulate the progression and immune microenvironment of gastric cancer by modulating the immune-gene signature, which included two immune genes (TAB1 and CXCR4)." (PMID 35509844, 2022). "It was found in the clinical sample studies of gastric cancer that positive SDF-1 and CXCR4 expression rates gradually increases along with gastric cancer progression, which was basically synchronous with the expression trend of VEGF in gastric cancer progression." (PMID 36131788, 2022). "This study showed that curcumol inhibited the NF-κB, SDF-1α, and CXCR4 expressions in the CAG model and gastric cancer cells, and also the viability, migration, and invasion of gastric cancer cells, inducing their apoptosis in animal level and in vitro cultured cells." (PMID 36159583, 2022). "Moreover, in gastric cancer, CTHRC1 was reported to promote tumor metastasis through the HIF-1α/CXCR4 signaling pathway." (PMID 34968391, 2021). "CXCR4 is an independent prognostic indicator for gastric cancer patients, which may help to improve the individualized prognostic prediction of GC and provide candidates for the diagnosis and treatment of GC." (PMID 34322132, 2021). "The involvement of CXCL12/CXCR4 signaling in tumor invasion and metastasis was also confirmed in other several cancer types, including non-small cell lung cancer (NSCLC), gastric cancer (GC), and prostatic carcinoma (PCa), and also linked to the promotion of cancer stem cell proliferation." (PMID 32466591, 2020). "Next, we analysed CXCR4 expression between 38 EBV-positive (proven by in situ hybridization with EBER1) and 48 EBV-negative gastric carcinoma patients via immunohistochemistry (IHC), and the results were consistent with the expression found in the GSE51575 dataset." (PMID 33052232, 2020). "CXCR4 is a stromal cell-derived factor-1 (SDF-1) receptor that reportedly promotes cancer progression, including cell migration, invasion, and seeding to distal tissues, and is abnormally over-expressed in gastric cancer tissues." (PMID 29069741, 2017). "In gastric cancer, RND3 promotes metastasis by enhancing expression of CXCR4." (PMID 27705942, 2016). "Although mounting data indicate that CXCR4 is expressed on the cell surface of gastric cancers, nuclear expression of CXCR4 in gastric tumors has not been yet reported." (PMID 24659999, 2014). "Like other chemokine receptors, CXCR4 has been shown to be expressed on cell membrane and in cytoplasm of many tumors including gastric cancer, but not in the nucleus." (PMID 24659999, 2014). "Collectively, these observations suggest that CXCR4 expression is increased in gastric cancer tissues compared with the paired non-tumoral tissues." (PMID 23936528, 2013). "Intratumoral CXCR4 expression (HR, 5.07; 95% CI, 2.02 to 12.68; P=0.001) and TNM stage (HR, 15.50; 95% CI, 4.64 to 51.85; P<0.001) were both recognized as independent prognostic factors for overall survival in 97 patients with gastric cancer." (PMID 23936528, 2013). "Regarding the mechanism of FMNP-labeled MSCs recognizing in vivo gastric cancer cells, we consider that CCL19/CCR7 and CXCL12/CXCR4 axis loops may be involved in this course." (PMID 22709686, 2012).
gastric cancer (continued). "There was neither a difference of CXCR4 expression in gastric carcinoma versus non-neoplastic tissue (p = 0.229) nor in nodal negative versus nodal positive gastric carcinoma (p = 0.22)." (PMID 20386750, 2010). "Survival analysis showed that CXCR4 expression in tumour cells of gastric carcinoma as well as in tumour microvessels had no impact on survival." (PMID 20386750, 2010). "The SDF-1/CXCR4 axis also improves the clustering of integrin β1 in GC cells and promotes FAK signaling, thereby accelerating gastric cancer (GC) invasion." (PMID 40352270, 2025). "Similarly, in gastric cancer, activation of the CXCL12/CXCR4 axis via the STAT3 pathway induces downregulation of E-Cadherin and upregulation of N-Cadherin, Vimentin, and Snail, enhancing EMT, migration, and the invasiveness of gastric cancer cells." (PMID 38920657, 2024). "However, the CXCL1/CXCL8-CXCR2 axis may also cooperate with other chemokines in gastric cancer cell migration, particularly C-X-C motif ligand 12 (CXCL12, stromal-derived factor-1 (SDF-1))-CXCR4." (PMID 37408240, 2023). "Thus far, there are no published reports on 68Ga-Pentixafor accumulation in gastric cancer; however, there is evidence from preclinical studies using GC cell lines that there is CXCR4 overexpression." (PMID 36140541, 2022). "Furthermore, we investigated whether the expression of VEGF, CXCR4, and MVD has a significant correlation with clinicopathological factors, survival outcomes, and tumor recurrence following the curative resection of gastric cancer." (PMID 35877436, 2022). "Finally, we found that the imbalance of 11 immune regulatory factors could predict the overall survival time of gastric cancer, including EZH2, NRP1, CD59, OsBPL1aBCL11B, BASP1, HNMT, CXCR4, ASGR2, ANXA5, CDH2." (PMID 34322132, 2021). "The CD26-positive cells and CXCR4-positive cells accounted for 2.59 and 0.929% of the gastric cancer cells, respectively, and the double-positive cells and double-negative cells accounted for 0.995 and 95.5% of the gastric cancer cells, respectively." (PMID 27524415, 2017). "Therefore, the contribution of Cxcl12/Cxcr4 in antral stem cells and other form of gastric cancer has not been fully elucidated." (PMID 29340033, 2017). "Compared with week non-tumoral CXCR4 density in gastric epithelial cells, intratumoral CXCR4 expression increased both in intestinal-type and diffuse-type gastric cancer." (PMID 23936528, 2013). "In our study, we first identified high intratumoral CXCR4 expression as an independent poor prognostic factor for overall survival following gastrectomy of gastric cancer patients, and only the patients with TNM stage iii+iv could be significantly stratified by intratumoral CXCR4 expression." (PMID 23936528, 2013). "In summary, we show that GPCRs are differentially expressed in gastric cancer tissue and may contribute to the tumour biology: tumours expressing both, CXCL12 in tumour cells and CXCR4 in tumour surrounding microvessels, show a highly significant association with local tumour growth and UICC stages." (PMID 20386750, 2010). "However, whether CXCR4/CXCL12 affected regorafenib sensitivity in gastric cancer cell has not been fully investigated." (PMID 28489887, 2017). "In addition, in order to determine whether intratumoral CXCR4 expression could stratify patients with TNM stage stratum, we evaluated the prognostic value of intratumoral CXCR4 expression and did stratified analyses of gastric cancer patients with TNM stage i+ii and TNM stage iii+iv respectively." (PMID 23936528, 2013). "Levels of CXCR4 and TNF-α mRNA were significantly higher in H. pylori-positive gastric cancers (n = 19) compared to H. pylori-negative ones (n = 15)." (PMID 20699000, 2010). "Therefore, it is feasible that miR-204-5p acts as an anoikis-promoting miRNA by regulating CXCR4, OCT1, etcetera, rather than SIRT1, in gastric cancer." (PMID 33435156, 2021).
gastric cancer (continued). "Although the role of SDF-1 in the promotion of invasive growth is well documented and the intracellular signals triggered by CXCR4 activation have been extensively investigated, the role of SDF-1/CXCR7 axis in regulating tumor growth of gastric cancer is not yet known." (PMID 27716367, 2016).
colon carcinoma (122 papers, 2006 to 2025). "Heightened expression of CXCR3 and CXCR4 has been implicated in promoting colon cancer metastasis to draining lymph nodes, thereby correlating with unfavorable prognoses for CRC tumors metastasizing to the liver and lungs." (PMID 39835121, 2024). "In UC-associated colon cancer, CXCR4 promotes the progression of the disease by recruiting immune cells and enhancing cytoskeletal remodeling through the lncRNA XIST/miR-133a-3p/RhoA signaling." (PMID 36061211, 2022). "The CXCR4/TGFβ signalling axis has been recently implicated in colon cancer metastasis to the liver, as CXCR4 and CAF markers such as α-SMA, vimentin, FSP1, and FAP were highly expressed in patient specimens of liver metastatic lesions." (PMID 33669775, 2021). "Upon analysis of CRC tumor methylation in the TCGA, we found that promoter CXCR4 5mC hypermethylation exists in a small subset of primary colon cancers and those primary tumors with metastasis exhibit loss of 5mC in the promoter region." (PMID 32110952, 2020). "CXCR4 is a direct target of miR-126 in human colon cancer cells, miR-126 is reversely associated with RhoA activity in vitro." (PMID 27517626, 2016). "For the mechanism of its repression of colon cancer proliferation and invasion, Li reported that miR-126 negatively regulates the expression of CXCR4 and inhibits the RhoA/ROCK (Rho-associated proteinkinase) signalling pathway." (PMID 28536606, 2016). "Our data showed that cancer located in the rectum was associated with a high content of CD133+CXCR4+ cancer cell compared with colon cancer." (PMID 22871210, 2012). "Importantly, the epithelial-mesenchymal transition (EMT) of CD133 + CXCR4+ cells, which was strongly associated with liver metastasis of colon cancer, was also suppressed by giving 5-Fu/P85 copolymer micelles." (PMID 26864651, 2016). "Moreover, high CXCR4 expression could more effectively predict the efficacy of first-line treatments and was associated with worse outcomes in colon cancer patients." (PMID 40607416, 2025). "The CXCL12/CXCR4 axis is a critical target for inflammation-driven CRC progression, and high CXCR4 expression in patients with colon cancer increases the risk of recurrence and poor survival." (PMID 39804065, 2025). "They found a 66.7% positivity rate for CXCR4 expression, which was prevalent in right-sided colon cancers and higher-grade tumors." (PMID 40607416, 2025). "In general, the findings suggest that targeting CXCR4 with Pep R enhances the effectiveness of colon cancer treatment by reducing stem-resistant cancer cell proliferation, reversing EMT-induced markers, and inhibiting cell growth." (PMID 39070795, 2024). "On the other hand, the reduction in SDF-1α in metastatic CRC is likely attributed to the SDF-1α-CXCR4 interaction and thus promotion of epithelial to the mesenchymal transmission of colon cancer cells, and hence metastasis." (PMID 38954024, 2024). "MIF/CXCR4 axis were reported to induce an aggressive phenotype by inducing proliferation, adhesion, migration, and invasion of the colon cancer cells." (PMID 36417130, 2023). "Previously, we demonstrated that restoring CXCR4 reversed the inhibition effects of miR-126 on promoting the migration, proliferation, and invasion of colon cancer cells." (PMID 35615089, 2022). "Another example has been described where Lgr5+/CXCR4+ colonic cancer cells respond to the properties of CSCs through a greater ability to form spheres in vitro, develop tumors in vivo and resist chemotherapy." (PMID 35406582, 2022). "The expression of CXCL12 and its ligand CXCR4 are independent prognostic factors for the 5‐year disease‐free survival rate of patients with colon cancer." (PMID 35363937, 2022). "In search of pro-apoptotic mechanisms for CXCR4 mediated drug resistance; we discover that DR5 is a new selective target of CXCR4 in breast and colon cancer." (PMID 33966046, 2021).